MT-TI (mitochondrially encoded tRNA-Ile (AUU/C))
Synonyms: trnI; formerly MTTI
Gene: Mitochondrial transfer RNA gene on chromosome MT (4,263 to 4,331, forward strand). Ensembl gene ENSG00000210100.
Gene-disease validity (ClinGen):
ClinGen rates the evidence that MT-TI causes each of these diseases.
mitochondrial disease (mitochondrial): Definitive.
hypertrophic cardiomyopathy (mitochondrial): Moderate. A condition in which the myocardium is hypertrophied without an obvious cause.
Leigh syndrome (mitochondrial): Limited. A progressive neurological disease defined by specific neuropathological features associating brainstem and basal ganglia lesions.
Diseases named in the same sentence as MT-TI in open-access papers:
MT-TI is named in the same sentence as 2 diseases in open-access papers, as found by Europe PMC text mining. Sharing a sentence is not in itself a finding about the gene and the disease. The quoted sentences say what the papers report.
Leigh syndrome (1 paper, 2022). "MT‐TI is a mitochondrial gene of which pathogenic variants may result in mitochondrial dysfunction and basal ganglia lesions, similar to what has been proposed for Leigh syndrome." (PMID 36699000, 2022).
MT-TI also shares sentences with these, for which no sentence is quoted: cardiomyopathy (1 paper).